IPPK (inositol-pentakisphosphate 2-kinase)
Description:
Phosphorylates Ins(1,3,4,5,6)P5 at position 2 to form Ins(1,2,3,4,5,6)P6 (InsP6 or phytate). InsP6 is involved in many processes such as mRNA export, non-homologous end-joining, endocytosis, ion channel regulation. It also protects cells from TNF-induced apoptosis.
Synonyms: C9orf12; INSP5K2; FLJ13163; IP5K; IPK1; bA476B13.1
Tractability: PROTAC: ubiquitination databases record sites on it.
Gene: Protein-coding gene on chromosome 9 (92,613,181 to 92,670,262, reverse strand). Ensembl gene ENSG00000127080.
Subcellular location: Cytoplasm; Nucleus
Subcellular location (Human Protein Atlas): Cytosol
Pathways (Reactome):
Metabolism: Synthesis of IPs in the nucleus; Synthesis of pyrophosphates in the cytosol
Gene Ontology:
Molecular function: inositol-1,3,4,5,6-pentakisphosphate 2-kinase activity; molecular adaptor activity; protein binding; ATP binding
Biological process: positive regulation of transcription of nucleolar large rRNA by RNA polymerase I; inositol phosphate metabolic process
Cellular component: nucleolus; cytosol; nucleoplasm; cytoplasm; nucleus
Genetic constraint (gnomAD): Loss-of-function variants: 15 observed, 45.68 expected, observed/expected ratio (o/e) 0.33, 90% interval 0.22 to 0.51. The upper end of that interval is the gene's LOEUF score, 0.51, which puts it in group 2 of 6, group 1 being the genes least tolerant of losing a copy. Missense variants: 443 observed, 538.07 expected, observed/expected ratio (o/e) 0.82, 90% interval 0.76 to 0.89. Synonymous variants: 226 observed, 215.33 expected, observed/expected ratio (o/e) 1.05, 90% interval 0.94 to 1.17.
Homologues: Orthologues: chimpanzee IPPK (99% identical), macaque IPPK (98% identical), rabbit IPPK (94% identical), pig IPPK (93% identical), rat Ippk (91% identical), dog IPPK (91% identical), mouse Ippk (91% identical), guinea pig IPPK (89% identical), tropical clawed frog ippk (57% identical), zebrafish ippk (55% identical), Drosophila melanogaster Ipk1 (30% identical), Caenorhabditis elegans ippk-1 (22% identical).
Diseases named in the same sentence as IPPK in open-access papers:
IPPK is named in the same sentence as 3 diseases in open-access papers, as found by Europe PMC text mining. Sharing a sentence is not in itself a finding about the gene and the disease. The quoted sentences say what the papers report.
HIV-1 infection (2 papers, 2021). The type species of lentivirus and the etiologic agent of acquired immunodeficiency syndrome (AIDS). "Independent of cell line tested and relative to complemented controls, IPMK KO and IPPK KO reduced HIV-1 infection by greater than 10-fold upon dosing cells with 0.78 or 1.56 nM LCV, respectively." (PMID 34613803, 2021). "HIV-1 infection was inhibited by greater than 20-fold in IPPK KOVector cells dosed with 10 μM (CEM) or 5 μM (MT-4) PF74." (PMID 34613803, 2021). "IPMK or IPPK KO had a minor effect on HIV-1 infection when cells were dosed with PF74 at concentrations of 1.25 μM or lower." (PMID 34613803, 2021). "At these concentrations, HIV-1 infection was more robustly inhibited in IPMK KOVector cell lines versus IPPK KOVector cell lines." (PMID 34613803, 2021). "Regardless of CEM clone tested, retroviral complementation increased target cell susceptibility to HIV-1 infection (Flag-IPPK and IPMK-Flag cell lines), though not to the level observed in the original CEM cell line." (PMID 34613803, 2021). "HIV-1 infection of the E2 IPPK KO CEM clone was not affected, whereas the D10 IPPK KO clone exhibited increased susceptibility to infection by ~2 fold." (PMID 33476323, 2021). "The B6 IPPK KO clone supported a 2-fold increase in infection relative to WT cells, and IPMK KO cells had an insignificant increase, suggesting that IP6 does not play a significant role in initial HIV-1 infection of MT-4 cells." (PMID 33476323, 2021).
viral infection (1 paper, 2020). "If IP6 in the target cell is required for viral infection, one would expect to see a lower viral titer in IPPK-KO cells, regardless of the source of virus." (PMID 32776974, 2020).
infection (9 papers, 2014 to 2024). The state of being infected such as from the introduction of a foreign agent such as serum, vaccine, antigenic substance or organism. "To test the role of IP5 depletion in susceptibility of target cells, we next transduced the MINPP1-IRES-GFP vector or an empty IRES-GFP control into HEK293FT or IPPK-KO cells, and then tested their susceptibility to infection." (PMID 32776974, 2020). "Thus, the reduced infection previously observed using viral supernatant produced in IPPK-deficient cells was probably the result of a reduction in production rather than the ability of virions to infect, as demonstrated here for both IPPK and IPMK." (PMID 31851928, 2019). "On the other hand, infection of IPMK-KO or IPPK-KO target cells with normal MLV was somewhat less efficient than infection of controls; this is clearly contrary to results with HIV-1 5,25, which we confirmed as part of our study." (PMID 38464197, 2024). "In any case, the fact that MINPP1 reduced the infectability of IPPK-KO cells further supports the conclusion that infection by MLV depends upon the maintenance of proper IP5 and/or IP6 levels in target cells." (PMID 38464197, 2024). "Complementation of the IPPK KO cells line with IPPK rescued the infection of each IP6-dependent HIV-1 mutant to the extent that IPPK KOFlag-IPPK CEM target cells were 1.5 to 4-fold more permissive to each IP6-dependent CA mutant." (PMID 37267431, 2023). "In CEM IPPK KO cells, the extent of infection varied clonally, with values ranging from ~55 to 77% for clones B12, D6, E3 and G4 relative to infection of WT cells." (PMID 33476323, 2021). "To this end, we initially assayed the permissiveness of the IPPK KO CEM clones to single-cycle infection by VSVg-pseudotyped HIV-1 encoding a GFP reporter gene (HIV-GFPVSVg), scoring for infection by flow cytometric analysis of GFP expression." (PMID 33476323, 2021). "To test if IP6 in the target cell is required for susceptibility to infection, we infected HEK293FT or IPPK-KO cells with virus produced from either HEK293FT or IPPK-KO cells and compared infection levels." (PMID 32776974, 2020). "Addition of IP5 also promoted the accumulation of DNA, consistent with the infection data of viruses produced in IPPK-KO cells, which incorporate IP5 instead of IP6." (PMID 31851928, 2019). "By contrast, if IP6 is required for infection but can be derived from the producer or target cells, one would expect the virus to have a lower relative titer on IPPK-KO cells only when the virus is produced from IPPK-KO cells." (PMID 32776974, 2020). "Furthermore, we also found that HEK293 cells were more resistant to infection with influenza A virus upon over expression of either IPPK, PPIP5K1 or PPIP5K2." (PMID 24586175, 2014). "That there was no infectivity loss for any virus, WT or mutant, in IPMK or IPPK cells suggests either that IPs are no longer needed, virally packaged ligands are sufficient or that viruses can obtain sufficient quantities during infection despite the reduced levels." (PMID 31851928, 2019). "We found a highly reproducible reduction in infections in the KO cells, with a larger decrease in IPMK-KO than in IPPK-KO cells." (PMID 38464197, 2024). "Relative to WT and IPPK KOFlag-IPPK cells, IP6-depleted cells were >8-fold less sensitive to infection by HIV-1 CA P38A, K170A, K203A, or Q219A." (PMID 37267431, 2023). "By comparison to IPPK KO, IPMK KO decreased infection of IP6-dependent HIV-1 by >450-fold for each CA mutant relative to infection of either control cell line." (PMID 37267431, 2023). "In contrast to in vitro results, depletion of cellular IP5 and/or IP6 via IPPK or IPMK KO has, at best, a modest effect on target cell infection by HIV-1, even in T cells, indicating that these metabolites are dispensable in the context of the target cell." (PMID 37267431, 2023).
infection (continued). "Assays of Gag levels in IPPK KO CEM cells recapitulated the HIV-GFPVSVg results, with all clones except D10 being less permissive to infection than WT cells." (PMID 33476323, 2021). "By contrast, in CEM cells, we observed that HIV-1 single cycle infection was typically decreased in most IPPK KO and IPMK KO clones, with IPMK KO being more deleterious to single cycle infection." (PMID 33476323, 2021). "Detailed genetic and biochemical experiments demonstrated that the kinase activities of IPPK, PPIP5K1 and PPIP5K2 (which convert IP5 to1-IP7) were critical for both interferon induction, and the control of cellular infection by Sendai and influenza A viruses." (PMID 24586175, 2014). "It is therefore significant that we also found silencing of IPPK, PPIP5K1 and PPIP5K2 dampened IFNβ transcription during infection of HEK293 cells by Sendai virus (SeV), a known stimulator of RIG-I." (PMID 24586175, 2014). "IPPK KO, IPMK KO, and the respective control CD4+ MT-4 cells lines were challenged with the panel of IP6-dependent HIV-1 CA mutants and assayed for single cycle infection." (PMID 37267431, 2023). "Except for CA K170A, for which quantification of infection was limited by assay sensitivity (~1 infected cell per 300,000 cells), all IP6-dependent HIV-1 CA mutants were less infectious in IPMK KO cells compared to IPPK KO cells." (PMID 37267431, 2023). "We next corroborated the HIV-GFPVSVg single round infection results and simultaneously monitored HIV-1 particle production to determine whether HIV-1 release differs between WT and IPPK KO clones." (PMID 33476323, 2021). "HIV-1 spread remained delayed in all IPPK and IPMK KO clones tested even when the inoculum the was increased by 10- or 180- fold, confirming that the defect in spread was minimally dependent on multiplicity of infection (MOI)." (PMID 33476323, 2021). "We found that this treatment reduced infection of the IPPK-KO cells, while we could not detect an effect in the control cells or the IPMK-KO cells." (PMID 38464197, 2024). "To further confirm that the reduced infection of the KO cells resulted from the lack of the IPMK and IPPK, we tested whether transient transfection with expression vectors for the missing enzymes could reverse the effect." (PMID 38464197, 2024). "The knockdown of IPPK and PPIP5Ks did not significantly affect basal-level IFNβ or IFNα production when HEK293 cells were not stimulated by either RIG-I ectopic expression or transfection with poly (I:C) or infection with virus." (PMID 24586175, 2014).